CCR4 (C-C motif chemokine receptor 4)
Diseases named in the same sentence as CCR4 in open-access papers (continued):
Sharing a sentence is not in itself a finding about the gene and the disease.
asthma (continued). "It is associated with disease severity in conditions such as atopic dermatitis and asthma and regulates CCL5-induced mast cell migration via CCR4 in vivo." (PMID 40278124, 2025). "The role of several chemokine receptors in asthma has been reported - CCR4 was found to be highly expressed in Th2 cells, and CCL17/CCR4, CCL22/CCR4 mediated the migration of Th2 cells and triggered allergic airway responses." (PMID 36865551, 2023). "Platelets also express certain types of chemokine receptors (CCR3, CCR4, CXCR4) of pertinence to pulmonary cellular recruitment during asthma, although the physiological significance of these observations has not yet been fully elucidated." (PMID 33556295, 2021). "Kandace found that CCL17 can induce asthma and allergic diseases by releasing CGRP through CCR4 in respiratory epithelial cells." (PMID 34541002, 2021). "In addition to the role in atherosclerosis, studies have shown that CCR4 was expressed on platelets and triggered platelet activation and aggregation via binding to its ligands including macrophage‐derived chemokine in Th2 diseases such as asthma and atopic dermatitis." (PMID 31436916, 2019). "In asthma, increased CCL17 production by lung macrophages attract CCR4+ Th2 T lymphocytes, which play a central role in orchestrating airway inflammation." (PMID 30197642, 2018). "The percentage of CCR4+ in CD4+ T cells was significantly different between control subjects and patients with severe asthma based on the % predicted FEV1 (left)." (PMID 29507584, 2018). "The study of the compound 8a efficacy invivo demonstrated that CCR4 blockade by compound 8a effectively attenuate AHR, airway eosinophilia, and Th2 cytokines in a mouse model of OVA-induced asthma." (PMID 29118379, 2017). "CCR4 and its ligand CCL17 are up-regulated in the airways of asthmatic patients after challenge and contribute to the Th2 cell recruitment in asthma." (PMID 26003185, 2016). "Previously, an important role for CCR4 and its ligand CCL17 in Th2 T cell recruitment has been demonstrated in asthma." (PMID 25849971, 2015). "In keeping with a role for CCR4 on Th2 cells, anti-CCL17 and anti-CCL22 antibodies have both been observed to have efficacy in murine asthma models." (PMID 20011659, 2009). "Another CCR4 antagonist, GSK2239633, was developed with the intent to treat asthma, but was not pursued because of low bioavailability in healthy subjects and its inability to inhibit CCR4." (PMID 41291326, 2025). "Current common asthma therapeutics (including corticosteroids) were not able to affect the frequency of CCR4+CCR7+ memory CD4+ T cell subsets." (PMID 29507584, 2018). "Also, chemokine receptors like CCR3, CCR4, and CCR8 have been found to be elevated in asthma patients and experimental murine models." (PMID 27795621, 2016). "However, data from other studies indicate that the proportion of CCR4+ CD4+ T cells in peripheral blood or in the lungs does not always correlate with the severity of asthma." (PMID 29507584, 2018). "The mechanism could explain why Th2 cells migrate to asthma airways as T cells in bronchial mucosal or bronchoalveolar lavage fluid (BALF) of allergic asthma express CCR4, and meanwhile the levels of CCL22 in BALF but not Th1-selective chemokines are increased upon allergen challenge to the lung." (PMID 35000593, 2022). "Most allergic participants' responsive T cells had a C‐C chemokine receptor type 4 (CCR4) (+) phenotype, with a subset expressing CCR4(+) CCR6(+), regardless of asthma status." (PMID 41179368, 2025). "Immunofluorescent analysis of airway mucosal biopsies in patients with asthma showed that most T cells co-express IL-4 and CCR4, but, in contrast, T cells in airways of patients with COPD and pulmonary sarcoidosis produce IFN-γ and express high levels of CXCR3, while lacking CCR4 expression." (PMID 15526056, 2004).
adult T-cell leukemia/lymphoma (42 papers, 2011 to 2025). A peripheral (mature) T-cell neoplasm linked to the human T-cell leukemia virus type 1 (HTLV-1), adult T-cell leukemia/lymphoma is endemic in several regions of the world, in particular Japan, the Caribbean, and parts of Central Africa. "Both established cell lines and patient-derived cells were used for mogamulizumab (indication: CCR4-positive adult T-cell leukaemia)." (PMID 38167464, 2024). "ATXN1 or CIC alterations are present in 53% of adult T-cell leukemia/lymphoma (ATLL) cases, and CCR4 (C–C chemokine receptor 4) mutations are common, and the majority of ATLL patients exhibit CCR4 overexpression, which is associated with skin involvement and worse prognosis." (PMID 38178117, 2024). "Mogamulizumab is a C–C chemokine receptor type 4 (CCR4)-directed monoclonal antibody used for the treatment of relapsed/refractory mycosis fungoides (MF) or Sézary syndrome (SS), and adult T-cell leukemia/lymphoma (ATLL)." (PMID 37285523, 2023). "Prospective, observational, postmarketing surveillance conducted in patients with chemokine receptor 4 (CCR4)-positive, relapsed, or refractory adult T-cell leukemia-lymphoma (ATLL)." (PMID 38004412, 2023). "The use of a humanized anti-CCR4 antibody (mogamulizumab) for the treatment of adult T cell leukemia and cutaneous T-cell lymphoma has recently been licensed, highlighting the importance of CCR4 in tumor growth." (PMID 35222362, 2022). "CCR4 is also highly expressed in adult T-cell leukemia/lymphoma (ATLL) and cutaneous T-cell lymphoma (CTCLs)." (PMID 36385955, 2022). "CCR4 is also expressed in 30–65% of PTCLs, with expression seen in up to 90% of adult T-cell lymphoma (ATLL)." (PMID 34072040, 2021). "CCR4 is expressed on the surface of tumor cells of most patients with adult T-cell lymphoma/leukemia (ATLL) and is selectively expressed in other subtypes of peripheral T-cell lymphoma and cutaneous T-cell lymphoma." (PMID 34053802, 2021). "CCR4 is also widely expressed on the surface of tumor cells from patients with adult T-cell leukemia/lymphoma (ATL), peripheral T-cell lymphoma (PTCL) and cutaneous T-cell lymphoma (CTCL)." (PMID 34039310, 2021). "KW-0761 (mogamulizumab), developed by Kyowa Hakko Kirin (Tokyo, Japan) is an anti-CCR4 hIgG1 that favors ADCC and is clinically approved for the treatment of relapsed refractory CCR4+ adult T cell leukemia/lymphoma (ATCLL) and CTCL." (PMID 33924428, 2021). "First, mogamulizumab has been approved in Japan for relapsed or refractory CCR4+ adult T-cell leukemia-lymphoma (2012), PTCL (2014), and CTCL (2014)." (PMID 31192214, 2019). "This drug was approved in Japan for CCR4-positive adult T cell leukemia/lymphoma (ATL) in 2012, relapse/refractory CCR4-positive peripheral T cell lymphoma (PTCL) and CTCL in 2014." (PMID 27686492, 2016). "The clinical use of an anti-chemokine receptor mAb, mogamulizumab, specific for the C–C chemokine receptor type 4 (CCR4) has been granted in Japan for the immunotherapy of patients with relapsed or refractory CCR4+ adult T-cell leukemia (ATL)." (PMID 25688243, 2015). "Results of a phase 2 trial in 28 patients with R/R CCR4(+) adult T-cell leukemia/lymphoma (ATLL) showed an ORR of 50%, a median PFS of 5.2 months and OS of 13.7 months, which lead to its approval in Japan for this indication." (PMID 25355407, 2014). "CC chemokine receptor 4 (CCR4) is expressed in various types of PTCL including adult T-cell leukemia-lymphoma (ATL), which has the worst prognosis among them." (PMID 22538464, 2012). "Notably, it was first recognized as a treatment option for relapsed or refractory CCR4+ adult T-cell leukemia/lymphoma (ATLL) in Japan back in 2012." (PMID 38396877, 2024). "The CCR4 mAb KM2760 was originally employed to treat adult T-cell leukemia/lymphoma (ATLL)." (PMID 39290699, 2024).
adult T-cell leukemia/lymphoma (continued). "CCR4 is also widely expressed on surface of tumor cells of most patients with adult T-cell leukemia/lymphoma (ATL) and is selectively expressed in approximately 40% of patients with other subtypes of peripheral T-cell lymphoma (PTCL) and cutaneous T-cell lymphoma (CTCL)." (PMID 34039310, 2021). "Notably, mogamulizumab/Poteligeo, an anti-CCR4 targeted therapy for refractory adult T cell leukemia and mycosis fungoides has received FDA approval." (PMID 33329395, 2020). "Anti-CCR4 monoclonal antibody mogamulizumab has proven efficacy in T-reg-derived malignancies such as adult T-cell leukemia/lymphoma (ATLL) and CTCL." (PMID 38711850, 2024). "Mogamulizumab, a humanized anti-CCR4 monoclonal antibody, has been approved for the treatment of adult T-cell leukemia/lymphoma (ATLL)." (PMID 39840040, 2024). "HTLV-1 is the cause of adult T-cell leukemia/lymphoma (ATLL), a CD4 + CD25 + CD62L + FoxP3 + CCR4 + CADM1 + effector memory T-cell lymphoproliferative disorder that accounts for 5% of T-cell lymphomas and leukemias." (PMID 35056532, 2021). "CCR4 antagonists are used in the United States for the treatment of mycosis fungoides and Sézary disease, and used globally for the treatment of adult T-cell leukemia/lymphoma (ATCLL) and CCR4+ cutaneous T cell lymphoma (CTCL)." (PMID 32973504, 2020). "A previous report has shown that FOSL2 is constitutively expressed in adult T-cell leukemia (ATL), up-regulates CCR4 expression, and promotes ATL cell growth, together with JunD proto-oncogene, AP-1 transcription factor subunit (JUND)." (PMID 33385611, 2020). "CCR4 is also consistently expressed on the surface of tumor cells in T-cell malignancies, such as CTCL, including MF and SS, adult T-cell leukemia-lymphoma, and peripheral T-cell lymphoma (PTCL)." (PMID 31192214, 2019). "In adult T-cell leukemia/lymphoma (ATLL), ETS1 is highly expressed in patients of North American descent and promotes tumor growth by regulating CCR4, making it a potential therapeutic target." (PMID 40181983, 2025). "Moving away from anti-CD20 mAb, the anti-CCR4 mAb, mogamulizumab, is Food and Drug Administration (FDA) approved for use in adult T-cell leukemia/lymphoma (ATLL) as well as mycosis fungoids (MF) and Sézary syndrome, 2 subtypes of cutaneous T cell lymphoma (CTCL)." (PMID 33212886, 2020).
cutaneous T-cell lymphoma (40 papers, 2012 to 2025). "Mogamulizumab, an anti-CCR4 antibody that has been de-fucosylated, lowers the levels of CCR4+ T cells and CCR4+ Tregs in individuals with cutaneous T-cell lymphoma." (PMID 39143228, 2025). "High CCR4 expression also links the pathway to adult Tcell leukaemia–lymphoma and cutaneous T cell lymphoma." (PMID 41291326, 2025). "This antibody-based therapy has demonstrated efficacy in treating various cutaneous T cell lymphomas (CTCLs), including mycosis fungoides and Sézary syndrome, through the depletion of CCR4-expressing T cells by antibody-dependent cellular cytotoxicity (ADCC)." (PMID 40564964, 2025). "This interaction is essential in cutaneous T-cell lymphoma pathogenesis, as it allows CCR4-positive tumor T cells homing to the skin and attracts CCR4-positive Tregs to the tumor microenvironment." (PMID 36765704, 2023). "Mogamulizumab is a fully humanized, defucosylated anti-CCR4 antibody that was approved by FDA in 2018 for the treatment of relapsed/refractory cutaneous T-cell lymphoma." (PMID 37182149, 2023). "CCR4 in T cells has already been targeted in clinical trials with the anti-CCR4-antibody mogamulizumab in the therapy of cutaneous T-cell lymphoma." (PMID 37371612, 2023). "CCR4 is a promising target for antibody-based immunotherapy in cutaneous T-cell lymphoma (CTCL) and Tregs because of its high expression." (PMID 35222362, 2022). "In patients with cutaneous T cell lymphoma, mogamulizumab, a defucosylated anti-CCR4 antibody, reduced the levels of CCR4+ Tregs and showed significant efficacy." (PMID 34417572, 2022). "The investigators constructed an anti-CD30 CAR-T cell designated to treat r/r Hodgkin lymphoma and cutaneous T-cell lymphoma (CTCL) that incorporates C-C chemokine receptor type 4 (CCR4)." (PMID 36389658, 2022). "The anti-CCR4 antibody mogamulizumab has antitumor activity against cutaneous T-cell lymphoma by antibody-dependent cell killing, and has been already applied in a clinical setting." (PMID 34202088, 2021). "Based on the mechanism of CCR4, Mogamulizumab is a new humanized anti-CCR4 antibody that is currently being used in the clinical treatment of advanced cutaneous T-cell lymphoma (CTCL)." (PMID 33692955, 2021). "CC chemokine receptor 4 (CCR4) is highly expressed on regulatory T-cell subset (Tregs) and cutaneous lymphocyte antigen-positive skin-homing T cells including neoplastic cells of cutaneous T-cell lymphomas (CTCL)." (PMID 33260966, 2020). "The anti-CCR4 monoclonal antibody, Mogamulizumab, also shows promise in treatment of peripheral T-cell lymphoma and cutaneous T-cell lymphomas like mycosis fungoides and Sezary syndrome, by depleting CCR4+ malignant cells and CCR4+ Tregs." (PMID 29706961, 2018). "Recently, new agents targeting chemoattractant GPCRs have been developed and are being tested in the clinic, such as a humanized anti-CCR4 monoclonal antibody, mogamulizumab (KW-0761), aiming at curtailing cutaneous T cell lymphoma." (PMID 25110692, 2014). "Mogamulizumab, an anti-CCR4 monoclonal antibody, exhibits clinical activity in CCR4+ systemic and cutaneous T-cell lymphomas, and may be of some benefit in contrasting the cHL microenvironment." (PMID 33327433, 2020). "The anti-CCR4 antibody may be useful for therapy of ENKTL-NT as well as cutaneous T-cell lymphoma." (PMID 34202088, 2021). "For example, it has been shown that a fusion protein, composed of the truncated diphtheria toxin, IL-2, and an anti-CCR4 antibody generating a bispecific IL2-CCR4 IT, can be used for the treatment of cutaneous T-cell lymphoma (CTCL)." (PMID 39852848, 2025). "Mogamulizumab, an anti-CCR4 antibody, and brentuximab vedotin, a conjugated antibody against CD30, are FDA-approved for cutaneous T-cell lymphomas and showed good efficacy in previous studies." (PMID 38473222, 2024).
cutaneous T-cell lymphoma (continued). "As CCR4 monoclonal antibodies are FDA-approved for treating Sézary syndrome, an aggressive human cutaneous T-cell lymphoma, clinical investigations in canine glioma patients can support studies in human glioblastoma patients." (PMID 39046599, 2024). "NCT03602157 is a Phase I antiCD30 CAR-T cells co-expressing CCR4 for treatment of patients with Hodgkin ́s lymphoma and CD30+ cutaneous T-cell lymphoma (CTCL)." (PMID 35600381, 2022). "Another example is a humanized afucosylated anti-CCR4 antibody, mogamulizumab (trade name Poteligeo), which was approved by the FDA for cutaneous T cell lymphoma (CTCL) in August 2018." (PMID 32121592, 2020). "In Japan, this drug is approved for treatment of patients with different T cell malignancies such as relapsed/refractory (R/R) CCR4+ ATL and cutaneous T-cell lymphoma (CTCL)." (PMID 32547515, 2020). "In addition, CCR4 has been implicated in the pathogenesis of inflammatory diseases and cancer, being overexpressed in several T-cell disorders including adult T-cell leukemia–lymphoma (ATL), peripheral T-cell lymphoma (PTCL), and cutaneous T-cell lymphoma (CTCL)." (PMID 29387053, 2017). "The defucosylated human anti-CCR4 antibodies also demonstrated strong ADCC activity against Hodgkin’s lymphoma and cutaneous T-cell lymphoma cell lines and against the autologous Treg cells." (PMID 25080123, 2014). "Use of mogamulizumab (anti-CCR4) in patients with cutaneous T cell lymphoma or solid tumors, reduced the levels of circulating or intratumoral CCR4+ Tregs, respectively, but did not induce potent antitumor effects." (PMID 34177968, 2021).
COVID-19 (26 papers, 2020 to 2025). A disease caused by infection with severe acute respiratory syndrome coronavirus 2. "The mouse-Geneformer predicted that the activation of genes Cxcl3 and Ccr4 would induce a similar transition towards COVID-19-infected cells." (PMID 40106407, 2025). "A shift toward activated Treg subtypes was seen in patients with COVID-19 with increases in the activated CCR4+ (annotated as CCR4+), Helios–CCR6+ effectors, and several groups of proliferating Tregs." (PMID 36669118, 2023). "TH17 cells have been extensively studied using flow cytometry and in accordance with our results MHC-II positive as well as CCR4 positive cells were described in COVID-19 patients." (PMID 37730638, 2023). "We discovered several chemokine receptor signatures on NK cells (N = 8) associated with the development of severe COVID-19, including upregulated CX3CR1 expression on early NK cells and increased levels of CCR4, CCR9 and CXCR3 on terminal NK cells." (PMID 36433939, 2022). "There is a reduction in the percentage of ILCs, MAIT, NKT expressing CXCR3+ (and an increase in CCR4+), but it is expressed in γδ T cells in both moderate and severe COVID-19 patients." (PMID 35159352, 2022). "In our study, individuals recovered from severe COVID-19 had increased expression of lung-homing chemokine receptors CCR4, CXCR3 and CX3CR1 on NK cell subsets." (PMID 36433939, 2022). "Naïve and transitional memory (TM) CD8+ T cells from individuals suffered from severe and critical COVID-19 expressed higher levels of CCR4 (Bonferroni-adjusted P-value range 0.03–7 × 10−5)." (PMID 36433939, 2022). "A recent study investigating the immune cell transcriptome profiles of COVID-19 patients with pneumonia identified CCR4 expression as an upregulated target relative to healthy controls." (PMID 32973504, 2020). "However, evaluating the immunoexpression of CCR4, IL-4, Sphingosine-1 and Arginase, it is deduced that the COVID-19 group had the Th2 pathway activated." (PMID 36430210, 2022). "Interestingly, we revealed that patients with acute COVID-19, as well as COVID-19 convalescents, showed decreased frequencies of CCR4-expressing cells within all CD8+ T cell maturation subsets compared to healthy controls." (PMID 36146713, 2022). "Moreover, an increase in CD4+CD127-CD25+Treg cells was found in mild patients, and upregulation of CCR4 in activated CD8+T cells indicated enhanced lung homing in severe COVID-19 patients." (PMID 34603308, 2021). "Among COVID-19 convalescent patients with sarcoidosis we also found higher levels of T helper 1 cells and T helper 2 cells (with CXCR5–CCR6–CXCR3+CCR4– and CXCR5–CCR6–CXCR3–CCR4+ phenotypes, respectively) when compared to other groups." (PMID 41376646, 2025). "Increased expression of chemokine and cytokine receptors such as CXCR5, CCR4, CCR5, and CCR7 has been reported in both active and recovered COVID-19 individuals." (PMID 38357647, 2024). "CD4+ T cells primed in the setting of severe COVID-19 also appeared to have impaired Th1 memory formation, based upon decreased percentages of circulating CXCR3+CCR4– cells at early memory time points." (PMID 35857584, 2022). "Further, chemokine and cytokine receptors (CXCR3, CXCR4, CXCR5, CCR4, CCR5, and CCR7) expression was increased in active COVID-19 and recovered patients." (PMID 36532041, 2022). "Upon that, we noted a decreased percentage of CCR4-positive CD8+ T cells both in acute and convalescent COVID-19 patients." (PMID 36146713, 2022). "CXCR5 expression was altered in acute and convalescent COVID-19 subjects, whereas the frequencies of CXCR3+ and CCR4+ cells were decreased in both patient groups vs. HC." (PMID 36146713, 2022). "CD4+ T-cells in the COVID-19 group also had higher expression levels of the activation markers OX40 and CD69, as well as the chemokine receptors CCR6 and CCR4, than the other respiratory infection group, implying a stronger activation." (PMID 34835045, 2021).